IDH1 (isocitrate dehydrogenase (NADP(+)) 1)
Diseases named in the same sentence as IDH1 in open-access papers (continued):
Sharing a sentence is not in itself a finding about the gene and the disease.
angiomatoid fibrous histiocytoma (1 paper, 2024). "This includes a case of angiomatoid fibrous histiocytoma with EWSR1-CREM fusion, an angiocentric glioma with MYB-QKI fusion, a glioma with MYCN amplification, two patients with non-canonical IDH mutations (both with IDH1 R132S), and a patient with a KRAS mutation." (PMID 38764578, 2024).
Autoimmunity (1 paper, 2023). The occurrence of an immune reaction against the organism's own cells or tissues. "Similarly, examining how IDH1 impacts CTL activity in non-cancerous disorders is critical to understanding its potentially broader role in modulating tissue destruction during homeostasis, aging and autoimmunity." (PMID 37161052, 2023).
blast phase (1 paper, 2020). "Importantly, mutations in IDH1/2 or TET2 are not equally distributed across disease entities in that IDH1/2 are more frequent in blast phase disease whereas TET2 occurs with equal frequency in chronic and blast phase disease." (PMID 32781570, 2020).
bone chondrosarcoma (1 paper, 2024). A chondrosarcoma (disease) that involves the bone tissue. "We found that IDH1 R132 mutations were negatively associated with the prognosis of patients with bone chondrosarcomas." (PMID 38170705, 2024).
bone sarcoma (1 paper, 2023). A sarcoma that arises from the bone. "In bone sarcomas, MET CNV (n = 5) was the most frequent actionable GAs, followed by IDH1 SNV (n = 4) and FGFR3 SNV (n = 3)." (PMID 37546405, 2023).
Cachexia (1 paper, 2023). Severe weight loss, wasting of muscle, loss of appetite, and general debility related to a chronic disease. "In contrast, they were dramatically increased by 3.4 fold and 2.3 fold, respectively in muscle gastrocnemius of the CT26-bearing cancer cachexia mice with IDH1 mutation compared with controls, respectively." (PMID 37741882, 2023). "D2HG was enriched in IDH1 mutant tumor and serum, which was consistent with clinical data showing that IDH1 mutation at R132 resulted in a high concentration of D2HG and high frequency of cachexia in cancer patients." (PMID 37741882, 2023). "Trim63 and Fbxo32 expression was increased by 2.3 fold and 1.4 fold, respectively, in CT26-bearing cachexia mice without IDH1 mutation." (PMID 37741882, 2023).
cardiac hypertrophy (1 paper, 2018). "Pathways unique to IDH1 mt top 1% enhancer probes included NFAT and cardiac hypertrophy, integrin pathway, focal adhesion, and actin nucleation by ARP–WASP complex." (PMID 29428975, 2018).
chondromyxoid fibroma (1 paper, 2024). An uncommon benign cartilaginous neoplasm arising from the bone. "It should be noted that no IDH1/2 mutations were found in another benign tumor, chondromyxoid fibroma (n = 4)." (PMID 38248076, 2024). "No IDH1 mutations were found in chondromyxoid fibroma (n = 4)." (PMID 38248076, 2024).
clear cell ovarian carcinomas (1 paper, 2017). "Meanwhile, there are no studies determining IDH1/2 mutations in clear cell ovarian carcinomas, which have a poorer prognosis than serous ovarian adenocarcinomas." (PMID 28403884, 2017).
cognitive decline (1 paper, 2023). "Thus, in the study we did not include eventual differences between patients with IDH1 mutated and wildtype tumours, which may be present even before surgery, which would also be important in the light of research findings regarding the different dynamics of cognitive decline after surgery." (PMID 37341199, 2023).
colorectal tumors (1 paper, 2016). "Here, 120 was selected as the cutoff point for IDH1-R132H in both gastric and colorectal tumors; scores from 0 to 120 were deemed as low expression while scores from 121 to 300 were considered as high expression." (PMID 27655638, 2016). "We analyzed gastric and colorectal tumors for IDH1-R132H expression." (PMID 27655638, 2016).
conjunctival melanomas (1 paper, 2021). "It is therefore possible that the 5-hmC loss observed in conjunctival melanoma can also be partially attributed to IDH1 mutations." (PMID 34198758, 2021). "However, in our study of the genomic and transcriptomic landscape of conjunctival melanoma, we identified IDH1 mutations in 29% of cases." (PMID 34198758, 2021).
cyst (1 paper, 2022). A sac-like closed membranous structure that may be empty or contain fluid or amorphous material. "Five tumors harbored IDH1 mutations; these were not different from wild type tumors with respect to tumor size (p = 0.55) or cyst volume (p = 0.29)." (PMID 35659255, 2022).
energy metabolism disorders (1 paper, 2017). "IDH1 dysfunction could induce energy metabolism disorders and cause the accumulation of ROS in cells." (PMID 28427200, 2017).
esophagus tumor (1 paper, 2019). "To further confirm the role of IDH1R132C mutation in enhancing erastin-induced ferroptosis, we overexpressed wild-type or R132C mutant IDH1 in KYSE-170 esophagus tumor cells which contain two wild-type IDH1 alleles." (PMID 31591388, 2019).
Fanconi anemia (1 paper, 2017). Fanconi anemia (FA) is a hereditary DNA repair disorder characterized by progressive pancytopenia with bone marrow failure, variable congenital malformations and predisposition to develop hematological or solid tumors. "Of these, three genes (isocitrate dehydrogenase 1 (Idh1), superoxide dismutase (Sod) 2, and Sod3) were upregulated and one gene (Fanconi anemia group C (Fancc)) was downregulated in the HFD + HW group." (PMID 28098768, 2017).
Gliosis (1 paper, 2012). Gliosis is the focal proliferation of glial cells in the central nervous system. "One of the specimens from LGG was categorised as gliosis based on IDH1 immunonegative when uncertainty remained regarding histopathology." (PMID 22729482, 2012).
granulosa cell tumor (1 paper, 2023). A slow-growing, malignant tumor, characterize by the presence of granulosa-like cells and Call-Exner bodies, that is almost always found in the ovary. "The IDH1 mutation in ovarian juvenile granulosa cell tumor and enchondroma." (PMID 37324278, 2023).
Hypercalcemia (1 paper, 2026). An abnormally increased calcium concentration in the blood. "The risk of hypercalcemia may be higher in older patients and those with IDH1 mutations." (PMID 42311264, 2026).
hypothyroidism (1 paper, 2021). Abnormally low levels of thyroid hormone. "These DEPs including Pygl, Pklr, Pc, Ehhadh, Acox1, Fasn, Acly, Acsl1, Acsl5, Pgm1, Suclg1, Gpt, Idh1, Fh, and Adh1 maight be as target proteins of AMR and its fractions for hypothyroidism." (PMID 33959028, 2021).
Immunodeficiency (1 paper, 2022). Failure of the immune system to protect the body adequately from infection, due to the absence or insufficiency of some component process or substance. "Patients with the IDH1 mutant subtype mainly exhibited an immunodeficiency pattern in m6A cluster A, whereas patients with the IDH1 wild subtype were characterized by an immune tolerance pattern in m6A cluster B." (PMID 35359993, 2022).
intestinal tumors (1 paper, 2025). "In intestinal tumors, TNF-α disrupts interactions between IDH1 and the deacetylase SIRT1, leading to decreased IDH1 protein stability." (PMID 40906076, 2025).
kidney tumors (1 paper, 2018). "The L-2HG enantiomer also presents oncometabolic DNA demethylation inhibitory effects in kidney tumors, however this is due to changes in L-2HG dehydrogenase rather than IDH1/IDH2." (PMID 29922517, 2018).
Leukocytosis (1 paper, 2026). "Leukocytosis at diagnosis, complex karyotype, and mutations of IDH1 and SRSF2 were correlated with lower survival in the univariable analysis." (PMID 42125699, 2026).
lipid metabolism disorders (1 paper, 2015). "Collectively, these findings uncover a novel miR-181a-IDH1 axis that has an important role in regulating lipid metabolism, and implicate miR-181a as a potential therapeutic target for lipid metabolism disorders." (PMID 25739786, 2015).
metastatic carcinoma (1 paper, 2018). A carcinoma which has spread from the original site of growth to another anatomic site. "Although the overall mutational burden was substantially higher in metastatic cancers, consistent with previous studies, the primary and metastatic cancers were remarkably similar in their subtype distributions, except that metastatic cancers harbored no IDH1 mutations." (PMID 29581876, 2018).
neuroepithelial tumors (1 paper, 2014). "Low-grade neuroepithelial tumors presenting in childhood rarely contain an IDH1:p.R132H mutation." (PMID 24529209, 2014).
Osteopenia (1 paper, 2022). Osteopenia is a term to define bone density that is not normal but also not as low as osteoporosis. "IDH1 mutation inhibits osteogenic differentiation, and P2RX7 mutation causes osteopenia exhibiting deficient periosteal bone formation." (PMID 35457039, 2022).
osteoporosis (1 paper, 2023). A condition of reduced bone mass, with decreased cortical thickness and a decrease in the number and size of the trabeculae of cancellous bone (but normal chemical composition), resulting in increased fracture incidence. "In this study, IDH1 was identified combined with machine learning prediction models and expressed significantly different in the analysis of diabetic osteoporosis subtypes." (PMID 37645416, 2023). "Ultimately, we identified IDH1 from 17 FRGs as a prospective indicator of diabetic osteoporosis subtypes, using multiple machine learning algorithms and validated by uniting external datasets." (PMID 37645416, 2023).
pituitary adenoma (1 paper, 2022). "Furthermore, a MS patient with jugular foramen chondrosarcoma and pituitary adenoma revealed the same IDH1 R132C mutation in both tumors by Sanger sequencing." (PMID 35765075, 2022).
pulmonary hypertension (1 paper, 2022). Increased pressure within the pulmonary circulation due to lung or heart disorder. "Among them, ENO1 and IDH1 were demonstrated to be aberrantly expressed in pulmonary hypertension, which provided strong support for our results." (PMID 35646965, 2022).
schwannoma (1 paper, 2024). A benign, usually encapsulated slow growing tumor composed of Schwann cells. "RNA sequencing showed IDH1/2 and MDH1/2, which produce α-ketoglutarate or succinic acid, respectively, were suppressed following schwannoma cell radiotherapy." (PMID 38216587, 2024).
signet ring cell adenocarcinoma (1 paper, 2022). "For example, the IDH1 mutations we detected by NGS in Idylla-detectable BRAF or KRAS mutation positive CRC specimens are associated with mucinous or signet ring cell adenocarcinoma, thus providing molecular support for the correct diagnosis that would not be possible from the Idylla results." (PMID 35627184, 2022).
small bowel cancer (1 paper, 2024).
spinal cord glioma (1 paper, 2020). A neoplasm that arises from glial cells in the spinal cord. "Similarly, IDH1 mutations were also not observed in another study of 25 cases of 2016 WHO grade IV spinal cord glioma." (PMID 32228694, 2020).
thyroid gland disorder (1 paper, 2015). A disease involving the thyroid gland. "The only significant non-pathological associations of purity we found were a history of thyroid gland disorder in THCA and presence of IDH1 mutation in LGG." (PMID 26634437, 2015).
Trisomy 8 (1 paper, 2021). "Trisomy 8 is frequently associated with mutations in driver genes including RUNX1, ASXL1, DNMT3A43, TET244, and IDH1 and IDH245." (PMID 34707142, 2021).
vascular malformation (1 paper, 2021). A non-neoplastic disorder that is the result of defects of vascular morphogenesis. "And recurrently mutated genes were identified in several vascular malformations as well including TEK/TIE2 mainly in venous malformations, GNA11/14 mainly in vascular tumors, KRAS/NRAS/RASA1/HRAS mainly in AVMs, GNAQ, IDH1/2, AKT1, PTEN and PIK3CA." (PMID 34736485, 2021).
vulvar tumors (1 paper, 2015). "We report a detailed study of 25 vulva tumors [22 SCC, 2 MM, 1 atypical squamous cell hyperplasia (AH)] analyzed for expression of the high-mobility group AT-hook family member genes HMGA2 and HMGA1, for mutations in the IDH1, IDH2 and TERT genes, and for methylation of the MGMT promoter." (PMID 25823555, 2015).
tumor (1,606 papers, 2010 to 2026). "Tumor size, dedifferentiated subtype, IDH1 mutation and the presence of IMP2 were identified as independent negative prognostic survival factors in ChS." (PMID 41752158, 2026). "While molecular classifications (e.g., IDH1/2 mutations) have improved prognostic prediction, they inadequately explain the immunosuppressive tumor microenvironment (TME) that drives LGG progression." (PMID 40130175, 2025). "The human tumor samples that metabolically resemble fly tumors showed strong enrichment for mutations in IDH1, GTF2I and ATRX." (PMID 40523311, 2025). "In our study, we analyzed the IDH1 genotype, verified through histopathology, because IDH1 mutation is associated with a more favorable prognosis in LGGs and serves as a critical marker for understanding tumor biology." (PMID 40299088, 2025). "Prior studies have investigated the link between IDH1/2 mutation status, tumor grade and overall survival, with mixed results on the effect of IDH mutation on survival." (PMID 40364090, 2025). "In contrast, patients who underwent chemotherapy, had MGMT promoter methylation, carried IDH1/2 mutations, or received ≥ 50% tumor resection demonstrated better survival outcomes." (PMID 41398783, 2025). "As a tumor driver, IDH1 mutations demonstrate particular promise as immunotherapeutic targets for vaccine development." (PMID 40661781, 2025). "The likelihood of an IDH1 mutation was 11.8% when the SMI blood flow architecture of the tumor tissue was distorted and enlarged, compared to a straight or branching structure with no blood supply." (PMID 40944023, 2025). "Among these, isocitrate dehydrogenase 1 (IDH1) mutations hold particular significance due to their strong association with tumor progression and treatment response." (PMID 40299088, 2025). "Tumor-driving IDH1 mutations affect residue R132, with R132H and R132C the most common, though more rare mutations, including R132G, R132L, R132S, and R132Q have been reported in patients." (PMID 40188944, 2025). "The oncometabolite R-2HG is produced by IDH1 or IDH2 mutations in tumor cells and accumulated in the tumor microenvironment to levels up to 30 mM." (PMID 41367876, 2025). "The metabolic characterization of GBM, particularly in relation to IDH1/2 mutations, provides critical insights into tumor adaptation and progression." (PMID 40628732, 2025). "In summary, this study elucidates a novel mechanism underlying cisplatin-induced nephrotoxicity and provides valuable insights for the development of personalized treatment strategies for tumor patients carrying the IDH1-R132H mutation." (PMID 39306640, 2025). "Tumor-associated mutations in IDH1/2 result in the accumulation of the oncometabolite 2-hydroxyglutarate (2-HG)." (PMID 41462671, 2025). "The IDH1 mutation is often considered an initiating event in tumorigenesis, being present in all tumor cells, making it an attractive therapeutic target, including for vaccine development." (PMID 40565099, 2025). "A typical property of GBM are the highly hypoxic areas where, instead, the carboxylation activity of wild-type IDH-1 is reductive and has been linked with tumor aggressiveness, invasion, as well as resistance to therapies." (PMID 41516249, 2025).